BCHE (butyrylcholinesterase)
Diseases named in the same sentence as BCHE in open-access papers (continued):
Sharing a sentence is not in itself a finding about the gene and the disease.
leukocytosis (1 paper, 2015). "As expected, WBCC did not correlate with the BChE activity (rs = −0.1, Spearman's rank correlation test), presumably due to the bimodal distribution of the WBCC during the immune response (leukocytosis and leukocytopenia)." (PMID 25762852, 2015).
lipid metabolism disorders (1 paper, 2024). "Notably, elevated BChE activity may reflect the extent of lipid metabolism disorders and IR in the body, which may also exacerbate the risk of cholesterol stones." (PMID 39399104, 2024).
liver failure (1 paper, 2025). A liver disease characterized by the liver losing or has lost all of its function. "Furthermore, the only FDA-approved small molecule inhibitor that was selective for BChE, tacrine, was discontinued for resulting in liver failure amongst a statistically significant number of patients." (PMID 41226162, 2025).
lung adenocarcinoma (1 paper, 2020). A carcinoma that arises from the lung and is characterized by the presence of malignant glandular epithelial cells. "BCHE (Butyryl cholinesterase) activity in lung adenocarcinoma is less than in the adjacent non-cancerous tissue; and BCHE is one of two potential diagnostic markers in plasma/serum for non-small cell lung cancer." (PMID 32998690, 2020).
lymph node metastases (1 paper, 2019). "Factors independently associated with shorter OS were low serum BChE levels, advanced FIGO tumor stage, larger tumor size, presence of lymph node metastases, and a patient’s age." (PMID 30737542, 2019).
marasmus (1 paper, 2018). The lack of sufficient energy or protein to meet the body's metabolic demands, as a result of either an inadequate dietary intake of protein, intake of poor quality dietary protein, increased demands due to disease, or increased nutrient losses. "Serum levels of BChE, total protein, and albumin are lower in malnourished children with marasmus than those measured in normal children; these values tend to increase after 3 weeks of nutritional rehabilitation, and a similar trend in serum levels of BChE has been observed in undernourished adults." (PMID 29736152, 2018).
ocular hypertension (1 paper, 2022). Abnormally high intraocular pressure. "The increase in the activity of acetylcholinesterase (AChE), butyrylcholinesterase (BuChE) and monoamine oxidase-A (MAO-A) is also responsible for the occurrence of HBP and an increased risk of developing ocular hypertension and related complications." (PMID 36362630, 2022).
osteoporosis (1 paper, 2024). A condition of reduced bone mass, with decreased cortical thickness and a decrease in the number and size of the trabeculae of cancellous bone (but normal chemical composition), resulting in increased fracture incidence. "We found that serum paraoxonase/arylesterase 1 (PON1) was positively associated with osteoporosis in East Asian, while cholinesterase (BCHE) was significantly associated with LS‐BMD, and apolipoprotein L1 (APOL1) was significantly associated with FN‐BMD and heel eBMD in European population." (PMID 37970652, 2024).
overactive bladder (1 paper, 2024). Symptom of overactive detrusor muscle of the urinary bladder that contracts with abnormally high frequency and urgency. "The β-adrenergic drug Mirabegron, a drug initially used for the treatment of an overactive bladder, has new potential indications and is hydrolyzed by butyrylcholinesterase (BChE)." (PMID 38792217, 2024).
parasitemia (1 paper, 2021). "From each subgroup, the parameters of parasitemia, histopathological analysis, butyrylcholinesterase activity (BuChE), and functional study of the colon were evaluated." (PMID 34787259, 2021).
periodontal disease (1 paper, 2024). "In patients with periodontal disease, ACh levels are significantly elevated in saliva and gingival crevicular fluid, whereas gingival crevicular fluid levels of butyrylcholinesterase, a serine hydrolase that catalyzes the hydrolysis of esters of choline, including ACh, are significantly decreased." (PMID 39551739, 2024).
pituitary adenomas (1 paper, 2021). "However, some variants were associated with the biochemical activities of GH-secreting pituitary adenoma, such as BCHE, DARS, NGDN, and UNC5B variants." (PMID 34400688, 2021). "The results from WES and targeted resequencing and clinical results from GH-secreting pituitary adenoma patients confirmed that variants in BCHE, DARS, NGDN, and UNC5B may be involved in GH secretion." (PMID 34400688, 2021). "Based on the ELISA and MTS assays, the variants in NGDN and BCHE may affect GH secretion and tumor growth in GH-secreting pituitary adenomas." (PMID 34400688, 2021).
pituitary tumor (1 paper, 2021). A benign or malignant neoplasm affecting the pituitary gland. "Furthermore, GH-secreting pituitary tumors with variants in BCHE, DARS, NGDN, and UNC5B presented high biochemical activities including GH and IGF-1." (PMID 34400688, 2021). "BCHE, DARS, NGDN, and UNC5B variants were associated with increased GH-secreting pituitary tumor biochemical activity, which was confirmed in vitro." (PMID 34400688, 2021).
pneumococcal pneumonia (1 paper, 2015). A febrile disease caused by STREPTOCOCCUS PNEUMONIAE. "Therefore, low serum ChE levels, including both acetylcholinesterase and butyrylcholinesterase, may enhance immunosuppression by accumulation of unhydrolyzed acetylcholine, leading to activation of the cholinergic anti-inflammatory pathway and resultant aggravation of pneumococcal pneumonia." (PMID 26608261, 2015).
poisoning (1 paper, 2018). A condition or physical state produced by the ingestion, injection, inhalation of or exposure to a deleterious agent. "Here, we present the results of a studyon the effectiveness of recombinant butyrylcholinesterase (BChE) in modelingorganophosphate poisoning caused by oral administration of paraoxon at a doseof 2 mg / kg." (PMID 30713772, 2018).
post-traumatic stress disorder (1 paper, 2021). An anxiety disorder precipitated by an experience of intense fear or horror while exposed to a traumatic (especially life-threatening) event. "BChE is involved in the metabolism of endocannabinoids, and endocannabinoids are negatively correlated with the development of post-traumatic stress disorder (PTSD)." (PMID 34062954, 2021).
preeclampsia (1 paper, 2023). Preeclampsia is a hypertensive disorder of pregnancy that is characterized by new-onset hypertension with proteinuria presenting after 20 weeks of gestation, and depending on mild or severe forms may initially present with severe headache, visual disturbances, and hyperreflexia. "Data of butyrylcholinesterase activity (mean ± SD) were extracted or calculated from the texts, tables or figures of studies reporting the enzyme activity of pregnant women with preeclampsia in comparison to healthy pregnant controls." (PMID 38022101, 2023). "Blood butyrylcholinesterase (BChE) activity has been found to decrease during pregnancy and reportedly decrease even more in preeclampsia (PE)." (PMID 38022101, 2023).
pregnancy hypertension (1 paper, 2023). "The related searching keywords included ChE, plasma ChE, serum ChE or BChE, and PE, pregnancy-induced PE, pregnancy-induced hypertension, and toxemia." (PMID 38022101, 2023). "Exclusion criteria were concerned with studies in women with pregnancy hypertension not reporting the occurrence of PE, studies without data on BChE activity in preeclamptic women, or studies not having a proper control group (healthy pregnancy)." (PMID 38022101, 2023).
respiratory depression (1 paper, 2013). A decrease in ventilation secondary to impaired signals from the central nervous system. "While all three mice receiving SC +0.9% saline succumbed to the SC-induced respiratory depression and subsequently died, all three mice receiving SC+15 U BChE survived." (PMID 23536865, 2013).
retinoblastoma (1 paper, 2025). A malignant tumor that originates in the nuclear layer of the retina. "Moreover, genome-wide methylation profiling of aqueous humor cfDNA has defined robust subtypes of retinoblastoma linked to clinical outcomes, identifying differentially methylated genes (e.g., TFF1, BCHE, PCDHB2, ADAM33) that correlate with aggressive disease and chemoresistance." (PMID 41150792, 2025).
skin aging (1 paper, 2023). The gradual irreversible changes in structure of skin that occur as a result of the passage of time.. "Molecular docking analysis showed that 8 key compounds had a high docked ability with AR, BCHE, HPGD and PI3, which were identified as specific biomarker for the diagnosis of skin aging." (PMID 37310405, 2023).
Sleep apnea (1 paper, 2023). An intermittent cessation of airflow at the mouth and nose during sleep is known as sleep apnea. "The expression levels of hub genes and sleep apnea-related genes were significantly correlated, among which KILH4 and BCHE were significantly positively correlated (Pearson r = 0.897), OR9A4 Significantly negative correlation with ADIPOQ (Pearson r = −0.762)." (PMID 38077447, 2023).
neurodegenerative disease (62 papers, 2012 to 2026). A disorder of the central nervous system characterized by gradual and progressive loss of neural tissue and neurologic function. "The usual aspects of neurodegenerative diseases include loss of cholinergic neurons and an increase in the activity of cholinesterase, butyrylcholinesterase (BChE), and acetylcholinesterase (AChE)." (PMID 36984777, 2023). "It was found that the methanol extract of P. fruticosa was able to efficiently reduce activities of enzymes linked to neurodegenerative disease including acetylcholinesterase, butyrylcholinesterase and tyrosinase." (PMID 35368464, 2022). "BChE is linked to neurodegenerative diseases as it hydrolyzes various choline esters." (PMID 40397045, 2025). "In addition, it also appraised their potential antineurodegenerative properties on the basis of their ability to inhibit enzymes associated with neurodegenerative diseases: acetylcholinesterase (AChE), butyrylcholinesterase (BChE), and tyrosinase (TYR)." (PMID 36014295, 2022). "Although it is primarily associated with lipid metabolism and fasting responses, dysregulation of BChE has also been reported in neurodegenerative diseases, systemic inflammation, and various cancers." (PMID 40678419, 2025). "Particularly, the inhibition effect on AChE (IC50: 16.116 μg/mL) and BChE (IC50: 8.556 μg/mL) suggests the potential therapeutic application of MLs in the treatment of neurodegenerative diseases such as Alzheimer's." (PMID 40351366, 2025). "The significant inhibition of AChE and BChE points to the possibility of using these compounds in the treatment of neurodegenerative diseases, such as Alzheimer’s disease, through a mechanism of inhibition of acetylcholine-degrading enzymes." (PMID 40286078, 2025). "Neurodegenerative diseases can see the involvement of some enzymes, such as acetylcholinesterase (AChE), butyrylcholinesterase (BChE), and tyrosinase." (PMID 36658323, 2023). "The capacity to inhibit enzymes that play a role in the progression of neurodegenerative diseases, such as acetylcholinesterase (AChE), butyrylcholinesterase (BChE), and tyrosinase was also studied." (PMID 37891906, 2023). "Increased activity of these enzymes, especially butyrylcholinesterase (BuChE), is observed in neurodegenerative diseases." (PMID 34208297, 2021). "The enzymes acetylcholinesterase (AChE) and butyrylcholinesterase (BChE) are primary targets in attenuating the symptoms of neurodegenerative diseases." (PMID 31899981, 2020). "Butyrylcholinesterase inhibitors are being developed for neurodegenerative diseases and their biological effects on MMC survival and proliferation should be investigated." (PMID 22860071, 2012). "The potent inhibitory activity of AChE and BChE indicates the potential use of these derivatives in the treatment of neurodegenerative diseases, while the ability to inhibit α-glucosidase suggests potential use in the treatment of type 2 diabetes by reducing carbohydrate absorption." (PMID 40286078, 2025). "This indicates that HA may be effectively appropriate for applications targeting neurodegenerative diseases such as Alzheimer’s, where BChE inhibition plays a significant therapeutic role." (PMID 41304964, 2025). "Organoruthenium complexes are very promising not only as anticancer agents but also as agents for symptomatic therapy of neurodegenerative diseases due to their inhibitory properties against both acetycholinesterase (AChE) and butyrylcholinesterase (BChE), as well as amyloid-β (Aβ) aggregation." (PMID 36769002, 2023). "Therefore, AChE and BChE inhibitors are now widely used in the treatment and prevention of neurodegenerative diseases." (PMID 35458770, 2022). "For this reason, an important issue in searching for new efficient treatments of neurodegenerative diseases may be the discovery of very effective butyrylcholinesterase inhibitors." (PMID 35630702, 2022).
neurodegenerative disease (continued). "Two mainstream hypotheses about the mechanism of BChE inhibition to treat neurodegenerative diseases." (PMID 34062954, 2021). "Therefore, using a selective inhibition of BChE to treat neurodegenerative diseases should be the focus." (PMID 34062954, 2021). "As a biomarker, BChE can predict the progression of neurodegenerative diseases." (PMID 34062954, 2021). "Among all the biological properties of EOs and their constituents, we are particularly interested in the inhibition of acetylcholinesterase (AChE) and butyrylcholinesterase (BChE), due to the serious implications that neurodegenerative diseases are ever-more producing in western countries." (PMID 34685911, 2021). "BChE is known to have a vicarious effect on ACh hydrolysis in neurodegenerative diseases." (PMID 33061920, 2020). "The cholinesterase inhibitory activity was 7.38 ± 0.03 and 5.74 ± 0.06 mmol GALAE/kg, for the inhibition of acetylcholinesterase AChE and BChE, respectively, showing that this plant is a candidate for the isolation of compounds that can be useful for the treatment of neurodegenerative diseases." (PMID 29734888, 2018). "Selective BChE inhibitors may also offer therapeutic benefits in other neurodegenerative diseases." (PMID 40563465, 2025). "Furthermore, we evaluated their potential health properties by studying their antioxidant and in vitro anti-inflammatory activities and in vitro inhibitory effects on three enzymes involved in neurodegenerative diseases (acetylcholinesterase, butyrylcholinesterase, and tyrosinase)." (PMID 38671929, 2024). "Furthermore, the evaluation of inhibitory activity on cholinesterase enzymes (AChE and BChE), as a therapeutic target for neurodegenerative diseases, was reported in species of the genera Allocetraria, Asahinea, Cetraria, Dactylina, Nephromopsis, Tuckermannopsis, Tuckneraria and Vulpicida." (PMID 36432187, 2022). "Research into the design and testing of selective BChE inhibitors continues to expand the understanding of their therapeutic potential, and they may ultimately serve as a critical component of future treatments aimed at slowing the progression of neurodegenerative diseases." (PMID 40563465, 2025). "A novel 4-methylthiocoumarin derivative has been studied against acetylcholinesterase, butyrylcholinesterase, BACE1, β-amyloid aggregation, and oxidative stress involved in the pathogenesis of this neurodegenerative disease." (PMID 35956851, 2022). "Furthermore, the oximes showed selectivity towards binding to the BChE active site and the determined enzyme-oxime dissociation constants supported work on the future development of inhibitors in other targeted studies (e.g., in treatment of neurodegenerative disease)." (PMID 28737687, 2017). "Thus, the inhibition of AChE, BChE, and TYR is considered an important strategy in the management of neurodegenerative diseases." (PMID 39202972, 2024). "Furthermore, we employed molecular docking and molecular dynamics studies of the phenolic compounds with the proteins AChE, BChE, and BACE-1 in order to evaluate the binding characteristics and identify potent anti-amyloid agents against the neurodegenerative diseases such as AD." (PMID 31319560, 2019).